CASP2 (caspase 2)
Diseases named in the same sentence as CASP2 in open-access papers (continued):
Sharing a sentence is not in itself a finding about the gene and the disease.
tumor (continued). "We have demonstrated that an AURKB/CASP-2 mechanism, regulated by the levels of BID, determines the fate of tumor cells after abrogation of the spindle assembly checkpoint by AURKB or TTK inhibitors." (PMID 37443114, 2023). "As activation of caspase-2 is required following MC to prevent survival of polyploid cells following failed mitosis and failure to repair damaged DNA, it will be important to examine in future, whether phosphorylation of caspase-2 at S384 also prevents its tumour suppressor function." (PMID 32811973, 2021). "As expected, there were extensive differences in gene expression when comparing the two different tumor types, including 6601 DEGs when comparing EμMyc to Th-MYCN tumors and 6674 DEGs in the EμMyc/Casp2−/− versus Th-MYCN/Casp2−/− tumor comparison." (PMID 30670683, 2019). "Consistent with a tumor progression function, we found higher expression of Megf6 in EμMyc/Casp2−/− and lower expression in Th-MYCN/Casp2−/− tumors." (PMID 30670683, 2019). "There was also a single overlapping gene; Megf6 (Multiple EGF-Like Domains 6) differentially altered in EμMyc/Casp2−/− and Th-MYCN/Casp2−/− tumors, and this was validated by quantitative PCR in additional tumor samples." (PMID 30670683, 2019). "Caspase-2-deficient embryonic fibroblasts could be readily transformed in vitro and displayed impaired apoptosis and abnormal cycling following DNA damage, implying that the DNA damage response (DRR) might represent an important tumor-suppressive mechanism involving Caspase-2 activation." (PMID 24281211, 2010). "Tumor nodules found in Casp2C320S lung (7% mice) and intestine (7% mice) were also observed in some Casp2−/− mice but not in WT Casp2+/+ mice." (PMID 41477850, 2026). "Another intriguing finding is the impact of p62 on caspase-2 in a non-cancerous cell line (HEK293T) as well as two tumor cell lines (U1810 and SK-N-BE), indicating the generality of this p62-dependent caspase-2 regulatory avenue." (PMID 39543123, 2024). "Moreover, the combined treatment of ACP52C and the CASP2 inhibiting peptide sensitized ACP52C‐resistant cancer cell lines and human primary tumor cells to ACP52C." (PMID 37845006, 2023). "The exact downstream signaling mechanism by which caspase-2 accomplishes its specific tumor suppressor functions is not clear." (PMID 35444189, 2022). "Taken together, this study uncovers a so far not understood mechanism of caspase-2 tumor suppressor function in human tumor cells." (PMID 35444189, 2022). "Together with our data presented here, this suggests that in tumour cells, AURKB may act to maintain caspase-2 in a phosphorylated inactive state, thereby preventing apoptotic cell death that contributes to therapy resistance." (PMID 32811973, 2021). "Tumor suppression by caspase-2 has also been reported to be independent of both PIDD1 and RAIDD in certain models." (PMID 33425918, 2020). "While this phenomenon has not yet been studied in the tumor models where caspase-2 has been shown to play a role, E2F1 is known to promote tumorigenic properties like proliferation, drug resistance, and metastasis." (PMID 33425918, 2020). "In vivo studies in mice indicate that the genetic loss of PIDDosome function does neither impair the DNA damage response nor affect the tumor suppressive capacity of caspase-2 presumably due to the compensation by PIDDosome-independent mechanisms." (PMID 31366165, 2019). "Interestingly, the pathways melanogenesis and Wnt signaling were identified in the DEGs from both [EμMyc/Casp2−/− v EμMyc] and [Th-MYCN/Casp2−/− v Th-MYCN] tumor comparisons." (PMID 30670683, 2019). "The results thus indicate that Caspase-2-mediated tumor suppression is independent of both Pidd1 and Raidd." (PMID 25857265, 2015).
tumor (continued). "Although caspase-2 knockout mice do not spontaneously develop cancers, more recent analyses of cancer-prone mice lacking this caspase have exposed a tumour-suppressor function." (PMID 27919034, 2014). "Caspase-2 has positive and negative effects on tumor growth in different cancer models." (PMID 42208898, 2026). "Immunohistochemical staining for the HCC marker, glypican 3 (GCP3) in livers harboring tumors, demonstrated positive staining in five of nine Casp2C320S and two of four Casp2−/− mice, while the two WT livers with tumor nodules were negative for GCP3, suggesting that these liver tumors were not HCC." (PMID 41477850, 2026). "In addition to intrinsic apoptosis, tumor-suppressive functions by caspase-2 are related to non-apoptotic functions such as genomic stability, autophagy, and control of the cell cycle checkpoint." (PMID 39851496, 2025). "Our finding indicates a novel mechanism of tumor-suppressive activities by caspase-2, and accordingly, inhibition of caspase-2-mediated NONO cleavage by TRIM25 may enrich the repertoire of transcriptional and posttranscriptional events." (PMID 39851496, 2025). "Amongst all caspases, caspase-2, functionally grouped as an initiator caspase, is the most evolutionally conserved and has been described to fulfill both apoptotic and non-apoptotic functions, including tumor suppression, cell cycle regulation, and DNA repair." (PMID 36171196, 2022). "Caspase-2 also acts as a tumor suppressor in non-hematologic malignancies." (PMID 33425918, 2020). "These disparate findings of caspase-2’s varying capacities in inducing apoptosis suggest that, while caspase-2 can induce apoptosis, it may perform other non-apoptotic functions that contribute to tumor suppression." (PMID 33425918, 2020). "The increased proliferation seen in the absence of caspase-2 in some but not all tumor models suggests that this effect could be tissue or cell type dependent." (PMID 33425918, 2020). "Interestingly, in addition to DNA damage-induced apoptosis caspase-2 exerts various important non-apoptotic functions including tumor suppression, maintenance of genome surveillance by controlling cell cycle checkpoints, and autophagy." (PMID 31366165, 2019). "In addition, recent data demonstrated that caspase-2 is critically involved in the control of various nonapoptotic functions, including tumor suppression, genomic stability, oxidative stress, and autophagy." (PMID 31842382, 2019). "The negative HuR-caspase-2 axis may offer a novel target for tumor sensitizing therapies." (PMID 31366165, 2019). "Understanding aneuploidy tolerance mechanisms more widely, and the BCL9L/caspase-2/BID axis specifically, may unravel potential vulnerabilities in aneuploid cancers, which could be exploited to limit intercellular heterogeneity, a substrate for selection and tumor evolution." (PMID 28073006, 2017).
tumor (continued). "The extrinsic apoptotic pathway (which does not require Bak/Bak or caspase 2/9) could not compensate for inhibition of the intrinsic apoptotic pathway in our findings, contrasting with the classical model in which CTLs primarily kill tumor cells through activation of extrinsic apoptosis." (PMID 39711535, 2024). "Finally, we anticipate that perturbations of signaling pathways controlling the negative HuR-caspase-2 axis via inhibition of the different tumor-suppressive activities by caspase-2 may have a strong pathophysiological impact for colon carcinogenesis and therapy resistance." (PMID 31366165, 2019).
cancer (73 papers, 2009 to 2026). A tumor composed of atypical neoplastic, often pleomorphic cells that invade other tissues. "Caspase 2 deficiency results in the predisposition of cancer cells to aneuploidy, due to B-cell CLL/lymphoma 9-like (BCL9L) protein dysfunction." (PMID 36430734, 2022). "As a result, reducing caspase activity is a common pathway by which cancers avoid apoptosis, with reduced expression or mutations reported for both initiator (caspase 2, 8, and 10) and executioner caspases (caspase 3, 6, and 7) in a range of cancers." (PMID 35401556, 2022). "Caspase-2 cleaved one of these proteins, the cancer-associated transcription factor Runx1, although with relatively low efficiency." (PMID 27919034, 2014). "Furthermore, the downregulation of caspase-2 was implicated in various types of cancers in patients." (PMID 32438737, 2020). "Caspase-2 is also implicated in other processes (cancer regulation and metabolism) and may take on a regulatory role in these processes as well." (PMID 24350060, 2013). "These include directly adhering to cancer cells, secreting short-chain fatty acids, inducing cancer cell DNA fragmentation and morphological alterations, modulating caspase-2 activity, and triggering apoptosis." (PMID 40230717, 2025). "Our results provide evidence for a novel function of caspase-2 in cell death regulation and open potential new avenues to exploit ferroptosis in cancer therapy." (PMID 38429264, 2024). "We demonstrate that increased acetyl‐CoA production by FAO contributes to DNA damage‐induced cell death by promoting N‐alpha‐acetylation of CASP2, highlighting the potential importance of this pathway in the regulation of chemoresistance of cancer cells." (PMID 38145969, 2024).
cancer (continued). "This study provides the first demonstration of an important and unprecedented function of caspase-2 in protecting cancer cells from undergoing ferroptotic cell death." (PMID 38429264, 2024). "We also found that caspase-2 is widely expressed in dozens of human cancer cells, which makes activation of caspase-2-mediated cell death a potential strategy to kill cancer." (PMID 38676703, 2024). "ANKRD1 shows increased expression during oxidative stress in bovine GC and DDIT4 (also called REDD1) is a regulator of caspase-2 (via the ATF4-dependent pathway) in human cancer cells." (PMID 36737804, 2023). "Our findings also suggest that ACP52C‐resistant cancer cells express higher levels of MDM2 p60 by the CASP2‐mediated cleavage of MDM2 p90." (PMID 37845006, 2023). "Collectively, the lack of studies and the differential correlation between levels of lncRNA and caspase-2 among cancer cell types make it difficult to conclude on the precise mechanisms of caspase-2 regulation by lncRNAs." (PMID 36171196, 2022). "Knockdown of HOTAIR, a lncRNA frequently overexpressed in various carcinomas and potential anti-cancer target, was shown to decrease miR-125a-5p and increase caspase-2 cleavage resulting in apoptotic death." (PMID 36171196, 2022). "So far, research focused on the interaction between miRNAs and caspase-2 in carcinomas is still limited and preliminary." (PMID 36171196, 2022). "Two of the identified genes (SLC22A3 and CASP2) were previously shown to be inversely correlated with cancer progression." (PMID 33509203, 2021). "Of note, PIDD1 and CRADD have been reported to activate caspase-2 in various cellular contexts, including DNA damage or centrosome amplification in cancer cells as well as amyloid-induced neuronal toxicity." (PMID 33414379, 2021). "The effects of F. alnus and P. harmala leaf extracts on caspase 2, 6, 8 and 9 activities were studied in selected cancer cells." (PMID 32847047, 2020). "A subsequent report suggested that caspase-2 can prime cancer cells for TRAIL-induced death and that caspase-2 is required for TRAIL-induced caspase-8 cleavage." (PMID 33425918, 2020). "In this review, aberrant splicing events in cancer-associated genes, namely BCL2L1, FAS, HRAS, CD44, Cyclin D1, CASP2, TMPRSS2-ERG, FGFR2, VEGF, AR and KLF6, will be discussed." (PMID 30463359, 2018). "Several other studies have also demonstrated caspase-2 activation in various types of cancer cells following induction of apoptosis by taxanes." (PMID 27049919, 2016). "Here, we report that microRNA miR-125a-5p decreases and releases caspase 2 to promote cancer cell apoptosis after HOTAIR knockdown." (PMID 26962687, 2016). "In this study, we showed that inhibition of caspase-2 suppressed apoptosis in TRAIL-treated cancer cells." (PMID 26000607, 2015). "As Raidd was reported to have a role in DNA-damage-induced apoptosis because of its ability to form a complex with Pidd1 and Caspase-2,19 we used different cancer models to evaluate the impact of Raidd in tumorigenesis induced by DNA lesions." (PMID 25857265, 2015). "TMEM106A induces cancer cell apoptosis through caspase-2/BID activation and the mitochondrial pathway." (PMID 24975047, 2014).